APOL1 (apolipoprotein L1)
Diseases named in the same sentence as APOL1 in open-access papers (continued):
Sharing a sentence is not in itself a finding about the gene and the disease.
kidney disease (continued). "The pathogenic role of APOL1 is emerging in several kidney diseases targeting podocytes and strong association between APOL1 high-risk Vs and progressive non-diabetic kidney disease, FSGS and HIVAN have been reported." (PMID 27599995, 2016). "Risk of advanced kidney disease is two to seven times greater for those carrying risk alleles of APOL1, as compared to controls." (PMID 27148508, 2016). "tarSVM filter also correctly predicted common variants implicated in APOL1-related kidney disease, tarSVM filter thus had an overall FDR of 5 % (1 of 20)." (PMID 27287006, 2016). "Recently, genetic variants in APOL1 were identified as risk factors for renal disease in people of African descent." (PMID 27252935, 2016). "Approximately 13% of African Americans carry two APOL1 renal-risk alleles, placing them at high risk for subsequent kidney disease." (PMID 27054572, 2016). "Individuals with genetic variants in the Apolipoprotein L1 (APOL1) gene have greatly increased risk of kidney disease." (PMID 27847659, 2016). "For example, an ancestral variant in the APOL1 gene, which encodes apolipoprotein-L1, is observed in higher frequency in African Americans, contributing to higher rates of cardiovascular and renal disease." (PMID 27722209, 2016). "Initial studies pointed to variants in the MYH9 gene (which is located closely to the APOL1 gene) as risk factor for kidney disease in African Americans." (PMID 27314022, 2016). "These APOL1 risk alleles for kidney disease have been associated with resistance to African trypanosomiasis and are geographically restricted." (PMID 27314022, 2016). "It is unclear how APOL1 genotypes contribute to kidney disease risk, progression, and cardiovascular morbidity in children." (PMID 27900314, 2016). "The association between these two APOL1 alleles and kidney disease has been widely replicated in a variety of samples sets and study designs." (PMID 25933006, 2015). "Initial reports associating APOL1 variants with kidney disease in African Americans identified two independent sequence variants, termed G1 and G2, which reside in a 10-kb region in the last exon of the gene." (PMID 26147622, 2015). "The pattern of inheritance of APOL1 associated kidney disease risk is essentially autosomal recessive." (PMID 25933006, 2015). "Emerging data point to an expanding role of APOL1 genetic aberrations implying that they are not limited to kidney diseases, but are also associated with increased risk of cardiovascular disease (CVD)." (PMID 26112018, 2015). "The high rate of kidney disease in African Americans has been shown to be largely due to two coding variants in the APOL1 gene." (PMID 25933006, 2015). "APOL1-associated kidney disease risk inheritance follows an autosomal recessive pattern: The relative risk of kidney disease associated with inheritance of two high-risk variants is 7–30 fold, depending on the specific kidney phenotype." (PMID 25933006, 2015). "Two coding variants in the APOL1 gene (G1 and G2) explain most of the high rate of kidney disease in African Americans." (PMID 25933006, 2015). "Few other studies have examined the association of APOL1 with milder forms of kidney disease and findings have varied." (PMID 25884165, 2015). "Since only 4% out of 13% of AAs expressing APOL1 variants develop kidney disease, it appears that in addition to the genetic markers, there has to be additional insult to make podocytes vulnerable to injury." (PMID 26106375, 2015). "The APOL1 gene, located on long arm of chromosome 22 (22q13.1), encodes a circulating protein, apolipoprotein-L1, with a role in both innate immunity and susceptibility to kidney disease." (PMID 25933006, 2015). "Risk of kidney disease conferred by APOL1 G1 and G2 variants follows an essentially recessive mode of inheritance." (PMID 25933006, 2015).
kidney disease (continued). "The APOL1 gene mutation, for example, is known to be associated with renal disease in African populations, younger age of onset of kidney disease and faster decline in kidney function." (PMID 25612312, 2015). "These SNPs were determined to be sentinels for risk alleles of the neighboring gene, APOL1, which demonstrated a stronger link to kidney disease." (PMID 24949636, 2014). "The odds of having advanced kidney disease are 2-7 times greater for those carrying risk alleles of either MYH9 or APOL1, as compared to controls." (PMID 23351121, 2013). "Our results demonstrate a likely contribution of MYH9 variant rs11089788 in the progression of CKD when co-inherited with CFHR5 nephropathy, but cast doubt on the recently alleged association with variation in the APOL1 gene that is closely linked to MYH9." (PMID 23516419, 2013). "Further work investigating the role of APOL1 variants in kidney disease should explore the effects of APOL1 on HDLc." (PMID 22973513, 2012). "The recent discovery of missense variants in the Apolipoprotein L1 gene (APOL1) that increase kidney disease risk among African Americans makes the understanding of the HDLc-kidney function association very timely." (PMID 22973513, 2012). "The APOL1 risk alleles for renal disease occur in more than 30% of those with recent African ancestry, but to date have not been observed in European Americans." (PMID 23110237, 2012). "Similarly, studies have demonstrated that suPAR binds to apolipoprotein L1 (ApoL1), a circulating protein whose genetic variants, G1 and G2, are associated with an increased risk of kidney disease in individuals of recent African descent." (PMID 41480757, 2026). "Notably, APOL1 high-risk variants strongly associated with kidney disease in African Americans show markedly lower frequency and attenuated effects in continental Africa, indicating potential distinct genetic architectures." (PMID 41667462, 2026). "Moreover, the MYH9 kidney disease risk association signals were nullified upon conditioning for the APOL1 risk alleles." (PMID 40643530, 2025). "Whether other factors, such as APOL1 variants, might have contributed to kidney disease remains unknown." (PMID 40630302, 2025). "High kidney disease risk of Africa has been linked to APOL1 high-risk alleles." (PMID 40027896, 2025). "Taken together, these two sets of results suggest that SCARB1 expression may be downregulated in those with kidney disease in APOL1 high-risk genotypes." (PMID 39448372, 2025). "It has been shown that a lower proportion of African ancestry among individuals with the APOL1 high-risk genotype may be associated with an increased risk of kidney disease." (PMID 39927257, 2025). "The APOL1 G1 and G2 variants are causal in multiple forms of kidney disease and are incompletely penetrant, leading to the “second-hit hypothesis” of immune system activation as a trigger for AMKD development." (PMID 40501951, 2025). "However, only a subset of individuals with APOL1 risk variants develop kidney disease, highlighting how other contributing factors trigger CKD progression or protect individuals from the disease." (PMID 39857298, 2025). "Genetic factors may also play a role; variants in the APOL1 gene, more common among people of African ancestry, have been associated with higher rates of various forms of kidney disease." (PMID 40725643, 2025). "Thus, any factors influencing APOL1 expression in renal cells will subsequently influence the risk of developing APOL1-mediated kidney disease post-transplant." (PMID 41010023, 2025). "First, genetic variations in protein metabolism and kidney disease susceptibility may modify dietary responses, as evidenced by differences in APOL1 gene variants that affect kidney disease risk predominantly in individuals of African ancestry." (PMID 40791237, 2025). "However, possessing two APOL1 high-risk alleles is strongly associated with kidney disease through gain-of-function toxicity." (PMID 41497611, 2025).
kidney disease (continued). "As a result, the novel APOL1 variant could potentially exert pathophysiological effects on renal disease by affecting the podocytes’ function." (PMID 40948471, 2025). "Furthermore, in our present study, the significant association signals for both variants disappeared when conditioning on APOL1 G1/G2 recessive risk, decreasing our confidence that they play an independent role in renal disease risk." (PMID 39163132, 2024). "This unified model holds that APOL1 G1–mediated (and G2 mediated) transport of Na+ and K+ across the PM is the proximal, causal driver of downstream signaling that terminates in cytotoxicity in general and podocytopathy in particular, a major cause of APOL1-mediated kidney disease." (PMID 38227370, 2024). "However, few genome-wide significant genetic variants have been identified that affect the APOL1 HR kidney disease relationship." (PMID 37962879, 2024). "The presence of two APOL1 risk alleles greatly increases the risk of various renal disorders." (PMID 39728069, 2024). "Ensuring that Gia’s content and design are culturally targeted for use among LKDs of African ancestry enhances Gia’s ability to reach and resonate with people who have been traditionally underserved, and are most at risk of kidney disease and APOL1 risk variants, and thereby increase its uptake." (PMID 38349598, 2024). "Another article describes the novel trypanolytic apolipoprotein L-1 (APOL1) variants specifically expressed in African Americans may contribute to the increased rate of renal disease." (PMID 38345042, 2024). "The prior division of APOL1 genotypes, such as 2 groups for one-risk allele and 3 groups for two-risk alleles, could result in misinterpretation when assessing the impact of APOL1 variants and categorizing APOL1-related kidney diseases." (PMID 38660426, 2024). "This is of particular interest considering the established risk of FSGS in African American patients harboring APOL1 risk alleles, and the faster rate of kidney disease progression observed among patients with CKD36 or FSGS37 with a high-risk compared to a low-risk APOL1 genotype." (PMID 38765567, 2024). "Therefore, we performed diagnostic genetic analysis based on whole-genome or exome sequence data in 3 cohorts, and evaluated the clinical outcomes of individuals with monogenic kidney disorders and APOL1 kidney risk genotypes." (PMID 39225089, 2024). "One such example of this is APOL1-associated kidney disease." (PMID 36853804, 2023). "APOL1 variations increase the risk of kidney diseases in African Americans." (PMID 38017264, 2023). "However, the putative evolutionary benefits come at a cost of increased lifetime risk for kidney disease in individuals with two copies of these variants (i.e., G1/G1, G2/G2, or G1/G2, identified as APOL1 high-risk genotypes)." (PMID 38036523, 2023). "Since the seminal discovery of the trypanolytic, exonic variants in apolipoprotein L1 (APOL1) and their association with kidney disease in individuals of recent African ancestry, a wide body of research has emerged offering key insights into the mechanisms of disease." (PMID 37461136, 2023). "Indeed, APOL1-mediated kidney disease has been stereotypically linked to several infectious triggers in epidemiologic studies and clinical reports." (PMID 37461136, 2023). "However the patients being ART naïve and having a definitive diagnosis of CKD with kidney histology adds to the strength of the association of HRG of APOL1 with specific forms of kidney disease among the study patients." (PMID 36227935, 2022). "The exposure to Trypanosoma sp infection could result in the development of 2 forms of high risk alleles associated with kidney diseases, referred to as APOL1 G1 and APOL1 G2." (PMID 36034035, 2022). "Despite the strong link between APOL1 polymorphisms and kidney disease, the molecular mechanisms via which these APOL1 mutations influence the onset and progression of CKD remain unknown." (PMID 36011371, 2022).
kidney disease (continued). "However, this outcome was modified by an awareness of patients’ genetic risk, with a higher increase in kidney disease screening among patients with high-risk APOL1 genotypes vs those with low-risk APOL1 genotypes." (PMID 35244702, 2022). "This may be explained by observations that APOL1 high-risk genotypes are more potent drivers of kidney disease (especially ESKD) in people with HIV compared with those without HIV,8,9 thus partially obscuring the effect of SCT." (PMID 35257059, 2022). "Common variants in the APOL1 gene are potent risk factor for a spectrum of kidney disease." (PMID 36580463, 2022). "We suggest that inhibition of APOL1 translocation into the lumen of the ER may serve as a potential therapeutic target that might mitigate APOL1 toxicity and the risk for kidney disease in individuals with the two APOL1 risk allele genotype." (PMID 35072009, 2022). "However, genotyping in the R3 study revealed lower than anticipated prevalence of the high-risk (HR) APOL1 genotype (6.2%), which has been associated with kidney disease risk." (PMID 35787257, 2022). "In addition, informing the detection of APOL1 variants, which are known to influence kidney disease risk, can help direct health resources and implement policies that promote well-being in populations of African descent." (PMID 36217118, 2022). "We determined that a single copy of a risk allele is insufficient to induce kidney disease in our model, and that the addition of a APOL1 G0 allele (heterozygosity) – if anything – increased proteinuria, but still to a level that is markedly reduced compared with risk variant homozygotes." (PMID 34350953, 2021). "In patients, APOL1 kidney disease appears to follow a two-hit model, whereby a genetic predisposition (presence of two APOL1 kidney risk alleles) is coupled with factors that increase APOL1 gene expression (interferon being the most well-documented)." (PMID 34765626, 2021). "However, to date, reported data on kidney disease associated with APOL1 RVs have been mostly limited to podocytes." (PMID 34440683, 2021). "However, it is still debatable if APOL1-associated kidney disease is due to loss-of-function or gain-of-function." (PMID 34442464, 2021). "Like HIVAN, COVAN is mostly reported in patients carrying risk variants of APOL1 supporting the hypothesis of a “second hit” necessary for the onset of APOL1-associated kidney disease." (PMID 35095882, 2021). "Similarly, APOL1 variants increase renal disease risk in the recessive model, possibly because a critical threshold of APOL1 protein level is required for cell toxicity." (PMID 33674766, 2021). "We quantified APOL1 protein levels in kidney, characterized mice that are either hemizygous or homozygous for the different APOL1 alleles, assessed the kidney disease phenotype of mice with different APOL1 genotypes and cross-bred mice to evaluate the concept of ‘G0 rescue’ on risk variant toxicity." (PMID 34350953, 2021). "Concerning these results, authors postulated that JCV may interact with APOL1 genotypes to modulate kidney disease risk." (PMID 34457361, 2021). "Whereas inheriting a single copy of the G1 or G2 APOL1 alleles is sufficient to enhance protection against resistant trypanosomes, inheriting two copies (one from each parent) substantially increases the risk of developing kidney disease." (PMID 34350953, 2021). "The functional roles of ApoL1 in human cells, the impact of the disease associated variants on these functions, and how any such alterations in activity may accelerate kidney disease are unclear." (PMID 33380423, 2021). "Taken together, these observations suggest that APOL1-targeted therapy for APOL1-associated kidney disease may be well-tolerated, except in regions with endemic African trypanosomiasis." (PMID 34765626, 2021). "Despite a decade of research, it is unclear how APOL1 risk variants cause kidney disease." (PMID 34350953, 2021).
kidney disease (continued). "Whether these ion permease activities play a role in pathogenesis of the ApoL1-associated renal diseases is unclear." (PMID 33380423, 2021). "We propose a model wherein APOL1 channel activity is the upstream event causing cell death, and that the activate-state, plasma membrane-localized channel represents the ideal drug target to combat APOL1-mediated kidney disease." (PMID 32427098, 2020). "As the lytic activity of APOL1 is sensitive to even single amino acid changes, it is imperative to only use the naturally occurring alleles to draw relevant conclusions regarding kidney disease." (PMID 32427098, 2020). "Although APOL1 renal risk variants are a risk factor for kidney disease in HIV-1 infected persons, it is unknown if APOL1 renal risk variants are associated with other HIV-1 phenotypes." (PMID 30733721, 2019). "The mechanism by which APOL1 causes kidney disease is not fully understood." (PMID 31929905, 2019). "Measured by the number of transcripts showing altered expression, podocytes undergo extensive transcriptional perturbation compared to endothelial cells and appear to be the most likely cellular location of pathology in APOL1 risk-variant associated kidney disease." (PMID 31158233, 2019). "Second, APOL1 variants are a major driver of kidney disease in HIV-positive persons." (PMID 31182139, 2019). "In addition, the prevalence of APOL1 risk variants for renal disease was found to be low among Ethiopians compared to other Africans." (PMID 30863641, 2019). "However, these APOL1 variants are also risk factors for kidney diseases, increasing the risk of CKD and ESRD in individuals of African and African-American descent." (PMID 30557319, 2018). "Genetic factors including polymorphisms in APOL1 may have an important contribution to the burden of kidney disease as shown by other studies." (PMID 30463531, 2018). "In this context, we speculate that the development of APOL1-related kidney disease could be mitigated even in the presence of risk alleles by preventing the formation of the tripartite complex." (PMID 29880816, 2018). "Therefore, we conducted a pilot study evaluating the feasibility of and willingness to participate in genetic research on kidney disease, and we estimated APOL1 risk allele frequencies among individuals with CKD." (PMID 28732083, 2017). "This low penetrance of the phenotype among patients with this genotype, coupled with undeniable association of the at-risk APOL1 genotype with renal disease, suggests the need for a “second hit” as well as a likely role for other genetic or environmental factors." (PMID 27600725, 2016). "Notably, the penetrance of the “at-risk” APOL1 genotype (homozygous or compound heterozygous for G1 or G2 allele) for kidney disease is much lower than that for other Mendelian diseases." (PMID 27600725, 2016). "Furthermore, the polymorphisms of other genes such as transforming growth factor-β1 (TGF-β1), non-muscle myosin heavy chain 9 (MYH9) and apolipoprotein L1 (APOL1) have been shown in associations with kidney diseases." (PMID 27114872, 2016). "However, additional, larger studies are required to conclude with confidence that the presence of multiple APOL1 copies contributes to kidney disease risk." (PMID 25933006, 2015). "Recent observations on the role of APOL1 variants in the development of kidney disease in AAs, it appears that heroin may have acted as a trigger for the induction of renal injury in this population." (PMID 26106375, 2015). "The presence of APOL1 duplication was observed in 4.06% of cases and 0.78% controls, preliminary evidence that this APOL1 duplication may alter susceptibility to kidney disease (p = 0.03)." (PMID 25933006, 2015). "Nevertheless, our study does provide an indication that APOL1 variants may play a role in conferring a poor renal disease and cardiovascular risk profile in this population." (PMID 26112018, 2015).